CD4 (CD4 molecule)
Diseases named in the same sentence as CD4 in open-access papers (continued):
Sharing a sentence is not in itself a finding about the gene and the disease.
autoimmune disease (1,397 papers, 2004 to 2026). A disorder resulting from loss of function or tissue destruction of an organ or multiple organs, arising from humoral or cellular immune responses of the individual to their own tissue constituents. "Autoimmune diseases in CD are caused by the consumption of gluten, resulting in gluten-specific CD4 + T cell responses and the production of antibodies against IgA-tTG." (PMID 41518458, 2026). "Autoreactive CD4+ T cell infiltration, tissue destruction, and spread epitope–specific CD4+ T cell activation underly CD4+ T cell–mediated autoimmune disease pathogenesis." (PMID 41481727, 2026). "Excessive activation of CD4+ T cells is a common hallmark of autoimmune diseases such as systemic lupus erythematosus and SS." (PMID 40426896, 2025). "By stimulating dendritic cells, aldosterone activates CD8+ T cells and polarizes CD4+ T cells to Th17, a phenotype associated with inflammation and autoimmune disease, secondary to the production of interleukin-6 (IL-6) and tumor necrosis factor-α (TNF-α)." (PMID 40426991, 2025). "CD4(+) T cells have been associated with the pathogenesis of various autoimmune diseases, including thyroid disorders such as autoimmune thyroid disease (AITD)." (PMID 39851522, 2025). "These genes encode molecules that regulate CD4+ T cell function and therefore play a critical role in the immune reaction and autoimmune diseases." (PMID 41510265, 2025). "Th17 cells, a unique subset of proinflammatory CD4 + T helper cells, are critical in mediating inflammatory responses to infections and are also implicated in the pathogenesis of autoimmune diseases and cancer." (PMID 40961099, 2025). "Th17 CD4+ T cells help B cells produce antibodies which protect against pathogens, while in susceptible hosts unwanted immune responses attack the heart in autoimmune disease states." (PMID 40181955, 2025). "Loss of function mutation in the Foxp3 gene (scurfy mice) leads to a fatal autoimmune disease characterized by hyperactive CD4 + T cells, and the animals succumb to death within 4 weeks of age." (PMID 39762647, 2025). "Multiple sclerosis (MS) is a demyelinating autoimmune disease mainly caused by the infiltration of myelin‐specific, self‐reactive CD4+ T cells into the central nervous system (CNS)." (PMID 40765112, 2025). "CD4(+) T cells, specifically, play a critical role in pathogen clearance, autoimmune disease regulation, and the elimination of pathogenic cells." (PMID 39851522, 2025). "CD6 is a risk gene for multiple autoimmune diseases, possibly related to its numerous roles in regulating CD4+T-cell responses." (PMID 39996744, 2025). "This pathway is associated with CD4+ T cell activation, differentiation, and cytokine secretion implicated in the pathogenesis of and a potential therapeutic target for autoimmune diseases including MS." (PMID 41282927, 2025). "In certain T cell–mediated autoimmune diseases like rheumatoid arthritis (RA), a paradox arises: CD4+ T cells can adopt a pathogenic effector state despite impaired T cell receptor (TCR) signaling." (PMID 39589811, 2024). "Th9 cells, a new subset of CD4+T cells with immunomodulatory properties, have been linked to the development of various autoimmune diseases." (PMID 38605942, 2024). "Several studies have demonstrated that an increased CD4/CD8 ratio is strongly associated with autoimmune diseases, including autoimmune blistering skin disorders such as BP and pemphigus vulgaris (PV)." (PMID 39553002, 2024). "NKG2D expression on CD4+ T cells has been associated with autoimmune disorders in mice and humans and has been linked to bystander activation on CD8+ T cells." (PMID 38838013, 2024). "In comparison, GzmB+CD4+ T cells, also known as CD4 CTLs, were mainly associated with viremic states and autoimmune diseases." (PMID 38968186, 2024).
autoimmune disease (continued). "Here, CD4+ T-cells following superantigen stimulation were used to investigate the mechanism of action in which abrin toxin triggers effects associated with autoimmune disease." (PMID 39727963, 2024). "Th17 cells represent a pro-inflammatory subtype of CD4+ T cells, that are critically important for the clearance of extracellular pathogens but also are often associated with autoimmune disorders." (PMID 38698860, 2024). "The trait-associated gene expression signature for autoimmune disease traits was polarized towards CD4+ T cell subtypes." (PMID 38590520, 2024). "Based on the observations that nematode coinfection is prevalent in areas where schistosomiasis is endemic and that nematode infection creates a host immune environment associated with attenuated incidence of CD4 T-cell-dependent autoimmune diseases." (PMID 39439825, 2024). "The cis-regulatory architecture of CD4+ T cells is enriched for autoimmune disease GWAS variants, and T cells from autoimmune patients harbor distinct epigenetic and transcriptomic signatures linking dysregulated gene expression with disease pathogenesis." (PMID 39302339, 2024). "CD4+ T cell-specific deficiency of SRC-2 results in resistance to autoimmune disorders and an impaired immune response, as has been demonstrated using experimental autoimmune encephalomyelitis (EAE) and colitis mice models." (PMID 38698860, 2024). "Here, we show that the MTX-101-mediated inhibition of inhibitory KIR on CD8 Treg enhances their activation, Granzyme B content, and ability to eliminate activated pathogenic CD4 T cells derived from individuals with autoimmune disorders." (PMID 39559361, 2024). "Antibody responses, involving B cells, CD4 + T cells, and macrophages, are implicated in autoimmune diseases and organ transplant rejection." (PMID 38649462, 2024). "The development and differentiation of CD4+ T cells are closely associated with the occurrence and progression of various immune-related diseases, such as cancer, autoimmune diseases, and hypersensitivity reactions." (PMID 38672418, 2024). "The evaluation of the CD4/CD8 T-cell ratio is critical in autoimmune diseases for both diagnostic assessment and disease monitoring." (PMID 39553002, 2024). "These CD4 + T lymphocytes are able to produce the pro-inflammatory interleukin 17 (IL-17) and seem to be associated with several autoimmune disorders." (PMID 39023839, 2024). "In particular, stratified linkage disequilibrium score regression (S-LDSC) has revealed the association between CD4+ T cells and autoimmune diseases by stratifying the heritability of polygenic autoimmune diseases by genetic features." (PMID 38359792, 2024). "According to a few publications about EOMES expression in CD4+ T lymphocytes, its up-regulation has been associated with a highly inflammatory phenotype in murine models and patients with autoimmune diseases." (PMID 39308517, 2024). "(A) The combination of evolutionary conservation (blue), open chromatin (red), and autoimmune disease-associated SNPs at the IL2 locus identify putative cRE in quiescent vs. 8 hr activated naïve CD4+ T cells." (PMID 39302339, 2024). "Metabolic abnormalities of CD4+ T cells have been implicated in the pathogenesis of autoimmune diseases such as rheumatoid arthritis (RA) and systemic lupus erythematosus (SLE)." (PMID 39039306, 2024). "Since B-cell differentiation is stimulated by CD4+ T-cells, their chronic activation leads to PH and increased production of autoantibodies, which are frequently found in PH-associated autoimmune diseases." (PMID 37497214, 2023). "For comparison, we analyzed a set of risk SNPs associated with systemic lupus erythematosus (SLE), an autoimmune disease whose outcome is less dependent on pro-inflammatory CD4 T cells than IBD." (PMID 37600767, 2023). "Human leukocyte antigens (HLAs) are pivotal in antigen processing, presenting to CD4+ T cells, and are linked to autoimmune disease susceptibility." (PMID 38202724, 2023).
autoimmune disease (continued). "The major pro-inflammatory CD4 T-cells associated with autoimmune diseases, including MS, are the Th1 CD4 T-cells." (PMID 36830745, 2023). "MG is a prototypical autoimmune disorder caused by specific autoantibodies at the neuromuscular junction, in which CD4+ T cells and B cells play important roles." (PMID 37223097, 2023). "A total of 245 candidate disease genes for autoimmune diseases were identified based on promoter CHi-C data in activated CD4+ T cells and genetic associations for five autoimmune diseases." (PMID 37346038, 2023). "RORγt is critical for mediating many autoimmune diseases, and pathogenic CD4+ T cells expressing RORγt contribute to neurobehavioral disorders by triggering brain inflammation." (PMID 37047547, 2023). "Increased expression of CREMα in CD4+ T-cells has been linked with effector cytokine expression in psoriasis, PsA and other autoimmune diseases, including SLE and juvenile idiopathic arthritis." (PMID 37662940, 2023). "Naïve CD4 + T cells isolated from Ets1 KO mice differentiate more readily to Th17 cells that secrete IL-17, a cytokine implicated in autoimmune disease pathogenesis." (PMID 37691956, 2023). "Th17 lymphocytes are a subset of CD4+ T cells implicated in the pathogenesis of various autoimmune diseases." (PMID 37680638, 2023). "Memory CD4+ T cells are highly associated with autoimmune diseases due to their long-lived properties, efficient responses to antigens and potential to mediate recurrent autoimmune responses." (PMID 36744136, 2023). "Since Clec4a is a negative immune regulator of DCs, mice deficient in Clec4a develop autoimmune diseases due to excess expansion of activated DCs and CD4+ T cells." (PMID 37892972, 2023). "Multiple studies have demonstrated that CD4+ Tregs are deficient and/or dysfunctional in autoimmune diseases, including RA, systemic lupus erythematosus (SLE), giant cell arteritis (GCA), PMR, and others." (PMID 36983342, 2023). "In many autoimmune diseases, CD4+ T cells have been implicated in mediating aspects of inflammation." (PMID 37649552, 2023). "The role of CD4+ T cells in the pathogenesis of autoimmune diseases has attracted attention based on their association with autoantibodies and MHC class II." (PMID 35880181, 2022). "It has been proven that, due to their greater susceptibility to autoimmune diseases, women have more circulating CD4+ T lymphocytes than men." (PMID 35053985, 2022). "Autoimmune disorders share common features such as the generation of pathogenic effector CD4+ and CD8+ T cells." (PMID 35883539, 2022). "Similar to that in TGF-β1–deficiency mouse, T cell–specific mutation or deficiency of Foxp3 results in lethal autoimmune diseases early in the life, whereas conditional knockout of Foxp3 in CD4+ T cells causes severe lymphoproliferative diseases." (PMID 36581209, 2022). "For seropositive autoimmune diseases, the primary HLA‐association is with HLA class II alleles suggesting a key role of CD4+ T cells." (PMID 35119226, 2022). "A decrease in TIGIT + CD4 + T cells was associated with severe forms of autoimmune diseases such as multiple sclerosis, atopic dermatitis, ulcerative colitis, and systemic lupus." (PMID 35821240, 2022). "Our study provides novel evidence that connects the metabolic regulation of CD4+ T cells and associated autoimmune diseases." (PMID 35211629, 2022). "The basic feature of RA is an autoimmune disorder in which autoreactive CD4+ T cells, pathogenic B cells, macrophages, inflammatory cytokines, chemokines, and autoantibodies are abnormally elevated." (PMID 35055087, 2022). "In the present study, we describe for the first time to our knowledge that SF CD1c+ cDC from patients with RA preferentially display a high capability to activate pathogenic IL-17+IFN-γ+CD4+ T cells involved in autoimmune diseases." (PMID 36194479, 2022).
autoimmune disease (continued). "The upregulated genes in CD4+ T cells from Ptenfl/flPf4-Cre mice implicated in multiple autoimmune diseases including systemic lupus erythematosus." (PMID 35589797, 2022). "Increased frequencies of TH2 and TH17 CD4+ T cells are associated with autoimmune diseases such as SLE, RA and systemic sclerosis." (PMID 36311777, 2022). "Changes in miRNA pool expression have been associated with differentiation of CD4+ T cells toward an inflammatory phenotype and with loss of self-tolerance in autoimmune diseases." (PMID 34041239, 2021). "Pathogenic CD4+ T cells in autoimmune diseases are characterized by increased glucose uptake and the upregulation of glycolytic enzymes." (PMID 33670988, 2021). "Altered number and/or function of regulatory T cells (CD4+CD25+ T cells) are known to be associated with autoimmune diseases, including MG." (PMID 34789272, 2021). "In particular, pathogenic CD4+ T cells in autoimmune disease are characterized by increased glucose uptake and the upregulation of glycolytic enzymes." (PMID 33670988, 2021). "Many studies have shown that the differentiation of CD4+ T cells into Th17 cells is a major cause of the occurrence and development of autoimmune diseases." (PMID 34234857, 2021). "Several studies have shown that regulatory CD4 + CD25+ T cells contribute much to controlling immune homeostasis, to maintaining self-tolerance, and to preventing autoimmunity, as impaired CD4 + CD25+ T cell activity can cause autoimmune disease." (PMID 33933004, 2021). "Patients with 18q deletions frequently suffer from autoimmune disorders, recurrent infections, and allergy due to immune dysregulation presenting with variable antibody deficiencies and T-regulatory cell deficiency (CD4+CD25+CD127lowFOXP3+)." (PMID 34867966, 2021). "Although USP12-deficient CD4+ T cells protected mice from autoimmune diseases, the immune response against bacterial infection was subdued." (PMID 33941870, 2021). "It is known that IL-9-producing CD4(+) T cells and IL-9 are associated with inflammatory bowel disease, tumor, and autoimmune diseases." (PMID 33941281, 2021). "Th17 cells are an important subgroup of CD4+ T cells, which play a major role in causing inflammation in autoimmune diseases." (PMID 35006213, 2021). "CD4 T cell subsets associated with T cell-mediated autoimmune diseases include T helper (Th) Th17 and Th1 cells." (PMID 34276700, 2021). "Plasticity is exhibited between CD4+ T cell subsets and linked to numerous maladies such as development and exacerbation of autoimmune disorders and tumorigenesis." (PMID 34759918, 2021). "Several studies have indicated that these senescent CD4+ T cells are associated with pathogenic features in chronic inflammatory diseases, including autoimmune diseases, cardiovascular diseases (CVD), diabetes mellitus (DM), and advanced age." (PMID 33808849, 2021). "Dysregulated immune cells, in particular CD4+ T cells, are amongst the cause and consequence of autoimmune diseases." (PMID 33467522, 2021). "Treg is a subset of CD4+ T cells which are characterized by the expression of transcription factor Foxp3 and helps to keep inflammation under control and lower the autoimmune disease risk in healthy individuals." (PMID 34305913, 2021). "Although USP12 deficiency protected mice from autoimmune diseases, it resulted in lower in vivo CD4+ T cell responses to L. monocytogenes infection." (PMID 33941870, 2021). "Autoimmune diseases are caused by unnecessarily aggressive autoreactive CD4+ T-cell responses that attack self-tissue and/or self-antigen." (PMID 31936879, 2020). "PD-1high memory CD4 T cells are pathogenic in autoimmune disease; here they show their expression of Egr2 is defective in rheumatoid arthritis and Egr2 & 3 control their inflammation and homeostasis." (PMID 32709717, 2020).
autoimmune disease (continued). "It was reported that a low baseline proportion of peripheral blood CD4+ Tregs was associated with subsequent colitis caused by ipilimumab, consistent with previous views that Tregs were capable of suppressing autoimmune diseases (ADs)." (PMID 33123120, 2020). "Functional deficits in CD4+ CD25+ FOXP3+ Treg cells after fludarabine treatment are one of the risk factors for autoimmune diseases in CLL patients." (PMID 33004832, 2020). "We have shown in prior studies that CD8-mediated suppressor function relies on granzyme- and perforin-mediated cytotoxic killing of pathogenic CD4+ T-cells or pro-inflammatory APCs in autoimmune disease, both in mice and humans." (PMID 33193343, 2020). "Those CD4+ T cell subsets have been implicated in the development of a number of autoimmune diseases including MG." (PMID 32148437, 2020). "Coeliac disease is another autoimmune disease caused by circulating Th1 CD4+ T cells which respond to gliadin derived peptides from oral food-derived gluten, and induce inflammation within the mucosa of the gastrointestinal tract." (PMID 33374787, 2020). "In summary, this is the first study to demonstrate the innate-like pathogenic function of bystander-activated CD4+ T cells in autoimmune disease progression driven by IL-1 and IL-23." (PMID 30755603, 2019). "The over-activation of CD4+ T cells and resistance to apoptosis are hallmarks of autoimmune diseases and also mechanisms underlying Th/Treg imbalances." (PMID 31284478, 2019). "Many HLA genes are strongly associated with autoimmune diseases as they stimulate self-antigen specific CD4+ T cells driving pathogenic responses against host tissues or organs." (PMID 31817224, 2019). "High expression of HLA class II risk genes is associated with autoimmune diseases, influencing the strength of the CD4+ T-mediated autoimmune response." (PMID 31817224, 2019). "It has been also implicated in tumor progression and autoimmune diseases and, together with CD4, is one of the co-receptors used by the HIV-1 virus to infect immune cells." (PMID 31507535, 2019). "Th17 cells are a recently identified CD4+ T subset with pro-inflammatory actions, and are associated with human autoimmune diseases." (PMID 31349846, 2019). "Th17 cells are a pathogenic effector CD4 T cell lineage that plays critical roles in the pathogenesis of some autoimmune diseases." (PMID 30764863, 2019). "Independently of any association with CMV, increased proportions of CD28null CD4 T cells have been implicated in a wide range of autoimmune diseases over more than two decades but also in atherosclerosis and coronary heart disease." (PMID 30984377, 2019). "For a long time, CD4+ T have been recognized as central players in the immune-pathogenesis of autoimmune diseases, which is supported by strong associations of rheumatic diseases with MHC class II alleles." (PMID 31143175, 2019). "The colonization of the small intestines of mice with segmented filamentous bacteria (SFB) induces the appearance of CD4+ T helper cells, promotes the production of Th17 cells, and induces autoimmune diseases, such as arthritis, in susceptible mice." (PMID 31709198, 2019). "Especially, the differential methylation of PTPRN2 in naive CD4+ T cell was associated with autoimmune disease, which suggested its role for immune response." (PMID 30890718, 2019). "In contrast to our limited understanding of the immune basis for T cell–mediated autoimmune disease, these clinical studies provided the opportunity to test the clinical effects of selectively engaging and activating pathogenic CD4+ T cells in patients." (PMID 31457091, 2019). "Studies in animal models of autoimmune diseases have shown that intracellular expression of IL-10 is linked to the ability of CD4+LAP+ cells to attenuate disease severity." (PMID 30425718, 2018).